RNU6-826P (RNA, U6 small nuclear 826, pseudogene)
Gene: Small nuclear RNA gene on chromosome 17 (49,036,352 to 49,036,455, forward strand). Ensembl gene ENSG00000252636.
Homologues: Orthologues: chimpanzee U6 (100% identical), macaque U6 (90% identical). Paralogues in human: RNU6-11P (90% identical), RNU6-37P (90% identical), RNU6-1 (88% identical), RNU6-1094P (88% identical), RNU6-2 (88% identical), RNU6-34P (88% identical), RNU6-3P (88% identical), RNU6-4P (88% identical), RNU6-5P (88% identical), RNU6-6P (88% identical), RNU6-7 (88% identical), RNU6-8 (88% identical), and 1287 more.